BMI1 (BMI1 proto-oncogene, polycomb ring finger)
Diseases named in the same sentence as BMI1 in open-access papers (continued):
Sharing a sentence is not in itself a finding about the gene and the disease.
cancer (continued). "In contrast, overexpression of Bmi-1 prevents cancer cell apoptosis, possibly by activation of nuclear factor kappaB (NF-kappaB) pathway signaling." (PMID 22967049, 2012). "Furthermore, Bmi-1-associated gene expression pathway, which is 11 gene Bmi-1 stem cell signature, is a powerful predictor of a short interval to distant metastasis, highly malignant clinical course of disease progression, and high likehood of therapy failure in multiple types of human cancer." (PMID 22209830, 2012). "Only 35.9% of matched adjacent non-cancerous tissues displayed the high Bmi-1 expression, whereas as many as 72.2% of the cancer tissues were defined by high Bmi-1 expression." (PMID 21276221, 2011). "Core pathway analysis revealed that 4 of these 12 target genes - Bmi1, Birc4, Bmpr2 and Ptpn12 - have been found to be significantly deregulated in cancer." (PMID 21846369, 2011). "BMI-1 is overexpressed in a variety of cancers, which can elicit an immune response leading to the induction of autoantibodies." (PMID 22132147, 2011). "Deregulation of polycomb genes is pervasive in human cancer and over-expression of BMI-1 and EZH2 contribute to the tumorigenicity of established ESFT cells." (PMID 21559395, 2011). "Among the genes up-regulated in holoclones, BMI1 has been shown to play key regulatory role in self-renewal of neural, mammary, hematopoietic stem cells and multi types of cancer stem cells." (PMID 21826251, 2011). "BMI-1 is essential for blood-cell development and the self-renewal capacity of several types of normal and cancer stem cells, and it is also important for cell cycle regulation, since both p16/INK4a and p14/ARF are downstream targets of BMI-1." (PMID 21311599, 2011). "Collectively, our data suggested that Bmi-1 plays a key role inregulating Snail expression and cancer stemness properties of HNSCC-ALDH1+ cells." (PMID 20936121, 2011). "Higher Bmi-1 levels are found in the cancer tissue, whereas the paired adjacent non-cancer tissue shows higher E-cadherin levels." (PMID 21276221, 2011). "Molecular investigations have suggested a role for BMI-1 by immortalization of mammary epithelial cells through induction of telomerase activity and regulation of cancer cells with stem-cell like properties." (PMID 21311599, 2011). "B-lymphoma Moloney murine leukemia virus insertion region-1 (Bmi-1) acts as an oncogene in various tumors, and its overexpression correlates with a poor outcome in several human cancers." (PMID 21276221, 2011). "b) Bmi-1 is required for self-renewal and maintenance of stem cells includingovarian cancer stem cells which by definition are resistant to chemotherapeutics." (PMID 21445297, 2011). "One of the first indications that PcG proteins play a role in cancer was the identification of BMI1 as MYC-collaborating oncogene." (PMID 22102868, 2011). "Such regulation of BMI1 is likely to be highly relevant for the role of BMI1 in development and pathobiology of various diseases, including cancer." (PMID 20569464, 2010). "Of special interest was the difference in transcription levels of Bmi-1 mRNA between non cancer controls and normal tissue from cancer patients (p = 0.041)." (PMID 21162745, 2010). "Abnormal expression of Bmi-1 has been found in several human cancers and its overexpression is often correlated with poor prognosis in many types of malignances." (PMID 21059209, 2010). "There is increasing evidence that the deregulated expression of BMI1 contributes to cancer development." (PMID 20569464, 2010). "In parallel with the upregulated Bmi-1 protein, four cancer cell lines and the immortalized NE-3 cells unexceptionally showed high level expression of Bmi-1 mRNA, while the normal esophageal tissue expressed a relatively low level of Bmi-1 mRNA." (PMID 20809956, 2010). "We also found that short-term telomerase inhibition results in decreased expression of genes, such as OCT3/4, NANOG, SOX2, and BMI1, that regulate normal and cancer stem cells." (PMID 20824134, 2010).
cancer (continued). "Consistent with our previous studies in other types of cancer, we found that Bmi-1 was overexpressed in immortalized esophageal epithelial cells and ESCC cell lines as well as in ESCC tissue both at transcriptional and translational level." (PMID 20809956, 2010). "Overexpression of Bmi-1 has been observed in a variety of cancers, and it has been suggested to be an independent prognostic marker for the patients." (PMID 20809956, 2010). "Bmi-1 is required for the proliferation of LSC/CSCs, and the deregulation of Bmi-1 is linked to human cancers." (PMID 20132553, 2010). "It's the first time to find that Mel-18 and Bmi-1 regulate cellular migration in in vitro model, and provide preliminary direct evidence for the possibility of Mel-18 and Bmi-1 regulate the metastasis of cancer." (PMID 20170541, 2010). "Bmi-1 mRNA level is consistently increased and Mel-18 mRNA level is consistently decreased in adjacent normal breast tissue of cancer patients as compared to normal breast tissue in women having had reduction mammoplasties." (PMID 21162745, 2010). "As Bmi1 is also a known oncogene, elevated in numerous types of cancer, the identified Bmi1/Ring1A ubiquitin ligase inhibitors can also be potentially used to directly target the oncogenic properties of Bmi1." (PMID 19956605, 2009). "Bmi1 is also involved in cancer by cooperation with Myc in lymphoma formation and blocking of senescence in immortalized mouse embryonic fibroblasts through repression of the Ink4a/Arf-locus." (PMID 19823589, 2009). "Several reports have shown that polycomb group transcription factor BMI1, is essential for the self renewal of hematopoietic, neuronal stem cells as well as cancer stem/progenitor cells." (PMID 19399189, 2009). "In invasive bladder cancers, expression of Bmi-1 protein in progression-free cancers was similar to that of cancers with progression (80.0% versus 82.4%, P > 0.5)." (PMID 19228380, 2009). "In invasive bladder cancers, the expression of Bmi-1 protein in progression-free cancers was similar to that of cancers that have progressed (80.0% versus 82.4%, P > 0.5)." (PMID 19228380, 2009). "A key component in the PRC2 complex is EZH2 histone methylase and similar to Bmi1, it is also elevated in various cancers." (PMID 19956605, 2009). "In the same line, co-labeling experiments with CTIP2 and CSC marker BMI1 highlighted the existence of a distinct subset of cancer cells (BMI1+/CTIP2+) with possible stem cell characteristics." (PMID 19399189, 2009). "Bmi1, a member of the polycomb group proteins, is required for self-renewal of neural stem cells and is upregulated in several cancers." (PMID 19823589, 2009). "This would facilitate a role of BMI1 in promoting cancer stem cells, which is in line with the reported up-regulation of genes involved in stem cell self-renewal in hTERT-immortalized human cells." (PMID 19903340, 2009). "Altogether, our results suggest existence of distinct subsets of cancer cells which express CTIP2 and underscore the use of CTIP2 and BMI1 co-labeling to identify tumor initiating cancer stem cells (CSC)." (PMID 19399189, 2009). "In tumor tissues, specific Bmi-1 signals were localized mainly in the nuclei of carcinoma cells in the form of yellow-brown granules." (PMID 19228380, 2009). "Based on their role in stem cells, EZH2 and BMI1 have been predicted to contribute to a poor outcome for cancer patients." (PMID 19099573, 2008). "BMI1 has been proposed to play a role in cancer stem cells or tumour-initiating cells because of its function in normal stem cells and its role as an oncogene." (PMID 19099573, 2008). "The Kruskal-Wallis test showed that cancer patients with the presence of Bmi-1 mRNA in plasma showed a tendency to have higher levels of Bmi-1 expression than healthy controls with Bmi-1 mRNA in plasma (p = 0.07)." (PMID 17711569, 2007). "All tested cancer cell lines expressed significantly higher level of Bmi-1 compared with those of NHOK." (PMID 17179983, 2007).
cancer (continued). "Cancer patients with the presence of Bmi-1 mRNA in plasma had higher levels of Bmi-1 expression than healthy controls with Bmi-1 mRNA in plasma." (PMID 17711569, 2007). "Bmi-1 expression is often deregulated in several types of human cancer, including hematological and solid tumors, which correlate with poor prognosis parameters." (PMID 17711569, 2007). "The level of Bmi-1 expression in the OSCC cells was comparable to that of the cancer cells, that is, RKO and HeLa, derived from other cancer types." (PMID 17179983, 2007). "Recent studies show that cancer and normal stem cells share the same self-renewal mechanisms, such as the Bmi-1 and Wnt canonical pathways." (PMID 17140455, 2006). "Moreover, FoxM1 can upregulate the expression of cancer stemness genes, such as BMI1, NANOG, and c-MYC, in HCC cells." (PMID 40050970, 2025). "Therefore, achieving the selective inhibition of BMI1 in tumor tissues while preserving its functionality in normal tissues is an important goal in cancer research." (PMID 40242481, 2025). "In several types of cancers, the expression of Bmi-1 is controlled by miRNAs." (PMID 39866230, 2025). "Moreover, PEITC targets multiple proteins, such as Bmi-1, to suppress various cancer-promoting mechanisms such as CSC proliferation, progression, and metastasis." (PMID 39866230, 2025). "Bmi-1 expression is frequently upregulated in various types of human cancers." (PMID 39866230, 2025). "Considering its role in chemoresistance and maintaining the self-renewal ability of CSCs, silencing BMI-1 may promote sensitivity to chemotherapy and prevent cancer relapse and metastasis." (PMID 41345229, 2025). "Additionally, BMI1 also functions as a stem cell factor, which enhances the stem cell phenotype of cancer cells in various malignancies." (PMID 40087716, 2025). "On the other hand, BMI-1 appears to be a significant target for cancer biology, regenerative medicine, and ageing-related research due to its involvement in epigenetic regulation, stem cell maintenance, cancer development, ageing, DNA repair, and immune system modulation." (PMID 38719848, 2024). "Bmi-1 is involved in the maintenance of stemness in normal and cancer cells." (PMID 38141761, 2024). "The polycomb E3 ubiquitin ligase subunits RING1A, RING1B, and BMI1, along with H2AK119ub1, help maintain the adult stem cell pool, and they may also contribute to the maintenance of cancer stem cells." (PMID 39620228, 2024). "Four out of eight cancer cell lines exhibited decreased Bmi-1 by SET KD." (PMID 38141761, 2024). "In addition to promoting acute leukemia, BMI1 promotes the proliferation of cancer cells in various solid tumors, including gastric cancer, pancreatic cancer, and epithelial ovarian cancer, by catalyzing H2A ubiquitination at lysine 119 (H2AK119ub)." (PMID 39620228, 2024). "Bmi-1 promotes cancer stemness not only as a subunit of PRC1 but also in a PRC1-independent manner." (PMID 38141761, 2024). "Notably, the widespread involvement of BMI1 in cancer provides a possibility for targeted therapy against BMI1 in human malignancies." (PMID 39349443, 2024). "Mechanistically, transcriptomic profiling of LINC00960-depleted cells confirmed its tumor-promoting role, likely through sponging of hsa-miR-34a-5p, hsa-miR-16-5p, and hsa-miR-183-5p, leading to the upregulation of cancer-promoting genes including BMI1, KRAS, and AKT3." (PMID 39039064, 2024). "We identified BMI1, MYC, NANOG, and OCT3/4 (POU5F1 gene) pluripotency markers as the most prominent transcription factors associated with HDAC2 gene expression, highly supporting HDAC2’s association with cancer stemness." (PMID 39063083, 2024).
cancer (continued). "Bmi-1, a polycomb-group transcriptional repressor, plays a pivotal role in numerous cellular functions, such as stem cell self-renewal and proliferation of cancer cells." (PMID 39057404, 2024). "In addition, BMI1, as a cancer stem-cell marker, participates in tumorigenesis through various pathways." (PMID 39769322, 2024). "Finally, the mouse orthotopic model demonstrated that co-administration of a BMI1 inhibitor with Bevacizumab enhances the anti-cancer efficacy of Bevacizumab in NSCLC, suggesting new avenues for clinical application." (PMID 39349443, 2024). "Moreover, downregulated cancer stemness proteins, including BMI1, c-MYC, and SOX2, were observed in EXOSC5 knockdown EC cells." (PMID 38164180, 2024). "Additionally, we performed IHC examination of our collected HCC patient cohort, indicating that in HCC patients, high expression level of BMI1 correlated with worse overall survival, increased tumor size and elevated cancer progression." (PMID 37923799, 2023). "Bmi-1 maintains and/or promotes the self-renewal of cancer stem-like cells/tumor-initiating cells in a variety of tumors, and thus is an ideal target for treatments aimed at cancer stem-like cells." (PMID 37219449, 2023). "However, aberrant expression of DLX6-AS1 disrupts miR-16 activation, thereby promoting the activation of oncogenes such as RICTOR and BMI1, contributing to cancer progression." (PMID 37767112, 2023). "Then, BMI-1 inhibition can be a promising approach to fight cancer." (PMID 38275623, 2023). "In this context, it has been found that BMI-1 inhibition increases the sensitivity of head and neck CSCs to cisplatin and that cisplatin resistance is due to the ability of BMI-1 to promote cancer cell growth and proliferation by activating the PI3K/Akt-dependent pathway." (PMID 38275623, 2023). "Targeting EMT inducers, such as EZH2 and BMI-1, may prevent cancer metastasis and improve the effectiveness of anti-cancer drugs." (PMID 36829176, 2023). "While these studies do not yet provide convincing evidence for Bmi-1 serving as a possible way to prognosticate treatment response, Bmi-1 is undoubtedly an important master regulator of cancer cell stemness and therapeutic resistance, rendering it a putative therapeutic target, nonetheless." (PMID 36726797, 2023). "Therefore, considering all the functions of BMI-1, it is reasonable to believe that its dysregulation can be a crucial factor in the onset of cancer." (PMID 38275623, 2023). "Based on our findings, we propose that inhibiting DLX6-AS1 activity could enhance miR-16 expression, which, in turn, can induce autophagy and apoptosis in cancer cells by inhibiting BMI1 and mTORs." (PMID 37767112, 2023). "We found that the perturbation scores of modules relating to mitosis, extracellular matrix, and RNA metabolism as well as transcriptional targets of polycomb group ring finger proteins BMI1 and PCGF2 were recurrently associated with disease progression in 3 or more cancers." (PMID 36950380, 2023). "BMI1 inhibitors for cancer treatment are yet in the research and development phase." (PMID 36909198, 2023). "In contrast, p16INK4A and BMI1 expression was altered depending on the sex and the presence of cancer in DM1 samples; it was decreased and elevated, respectively, in female patients with increased cancer risk, but the opposite was observed in males, in agreement with a previous study." (PMID 36040809, 2022). "Bmi1 overexpression has been previously reported in various types of cancers." (PMID 35342358, 2022). "Thus, the development of small molecule inhibitors against BMI1 will offer potential opportunities for cancer treatment." (PMID 36199791, 2022).
cancer (continued). "Besides EZH2, overexpression of other PcG proteins such as SUZ12 and BMI1 have also been shown to favor cancer progression." (PMID 35563864, 2022). "BMI1 is overexpressed in several human cancers, and known to be a poor prognostic factor." (PMID 36139536, 2022). "Some mitomiRs specifically regulate mitochondrial metabolism (mir-149 controls PARP2 and SIRT1 expression, mir-326 regulates PKM2 expression in cancer cells, mir-25 controls Ca uptake and ROS production, and mir-128a regulates BMI-1 expression to ensure redox homeostasis)." (PMID 36496979, 2022). "In conclusion, Bmi-1 has development potential as a target for the treatment of cancer." (PMID 35897796, 2022). "In this study, we interrogated RS through the prism of tumor-cell heterogeneity by measuring its level in breast CSCs (bCSCs) compared with mature cancer cells and revealed that bCSCs displayed a limited level of RS due to a constitutive activation of BMI1/RAD51 axis." (PMID 35110528, 2022). "In addition, several studies have found that the inhibition of BMI1 expression can reduce cancer resistance and suppress cancer progression." (PMID 36499676, 2022). "BMI1 gene amplification or protein overexpression has also been found in various cancer types." (PMID 35794816, 2022). "Furthermore, the unique biological functions and cancer-promoting effects of Bmi-1 have also attracted increased attention." (PMID 35897796, 2022). "Thus, the interaction between miRNA and Bmi-1 plays an important role in the occurrence and development of cancer." (PMID 35897796, 2022). "In addition, Bmi-1 is involved in the occurrence and development of many tumors, and the targeted therapy of cancer stem cells is an important measure for future development." (PMID 35897796, 2022). "Thus, it is possible to use the increased expression of the Bmi-1 gene in cancer cells as a survival marker." (PMID 35250573, 2022). "The Moloney murine leukemia virus insertion site 1 (BMI1) is a CSC marker found in several cancers." (PMID 35455671, 2022). "BMI1 has been demonstrated to participate in cancer radioresistance." (PMID 36362068, 2022). "With the development of molecular biological technology and the application of gene chip technology, development is expected of a microfluidic multi-indicator joint inspection chip, a circulating cancer-cell capture chip, and other devices for automatic detection of Bmi-1 expression." (PMID 35897796, 2022). "That was not surprising because, in many cancer cell types, BMI-1 downregulation causes inhibition of the AKT pathway." (PMID 36497428, 2022). "In addition, BMI-1 is overexpressed in gastric, colorectal, ovarian, breast, and other cancers, promoting cell proliferation and immortality by repressing transcription of the Ink4a/ARF locus." (PMID 36076977, 2022). "Interestingly, several recent studies have found that Bmi-1 is targeted and regulated by many miRNAs in cancer." (PMID 35897796, 2022). "It has been found that BMI-1 may also influence the AKT kinase pathway and that increased activity is associated with cancer onset and progression." (PMID 36497428, 2022). "However, future studies are needed to identify all players in the glucose- and BMI-1-dependent regulation of cancer onset and progression." (PMID 36497428, 2022). "The oncogenic role of BMI in oral carcinogenesis has been reported in various studies as it may enhance cancer stemness, and BMI1-positive cells in the lingual epithelium were suggested to be the cancer stem cells (CSCs) in tongue cancer." (PMID 34208375, 2021). "BMI1 expression is frequently upregulated in numerous malignancies, and accumulating evidence indicate that BMI1 is involved in the maintenance of cancer stem-like cells (CSCs)." (PMID 33804165, 2021).